LYPD6B (LY6/PLAUR domain containing 6B)
Description:
Likely acts as a modulator of nicotinic acetylcholine receptors (nAChRs) activity. In vitro acts on nAChRs in a subtype- and stoichiometry-dependent manner. Modulates specifically alpha-3(3):beta-4(2) nAChRs by enhancing the sensitivity to ACh, decreasing ACh-induced maximal current response and increasing the rate of desensitization to ACh; has no effect on alpha-7 homomeric nAChRs; modulates alpha-3(2):alpha-5:beta-4(2) nAChRs in the context of CHRNA5/alpha-5 variant Asn-398 but not its wild-type sequence. However, according to another report in vitro it can weakly inhibits alpha-7 nAChRs.
Synonyms: CT116; LYPD7
Tractability: Antibody: UniProt places it where antibodies can reach, with high confidence; its Gene Ontology location is reachable by antibodies, with high confidence; UniProt predicts a signal peptide or a membrane-spanning region.
Gene: Protein-coding gene on chromosome 2 (149,037,975 to 149,215,262, forward strand). Ensembl gene ENSG00000150556.
Subcellular location: Cell membrane
Pathways (Reactome):
Metabolism of proteins: Post-translational modification: synthesis of GPI-anchored proteins
Gene Ontology:
Molecular function: acetylcholine receptor regulator activity
Cellular component: extracellular region; plasma membrane
Genetic constraint (gnomAD): Loss-of-function variants: 13 observed, 17.66 expected, observed/expected ratio (o/e) 0.74, 90% interval 0.48 to 1.17. The upper end of that interval is the gene's LOEUF score, 1.17, which puts it in group 5 of 6, group 1 being the genes least tolerant of losing a copy. Missense variants: 188 observed, 236.08 expected, observed/expected ratio (o/e) 0.8, 90% interval 0.71 to 0.9. Synonymous variants: 88 observed, 83.88 expected, observed/expected ratio (o/e) 1.05, 90% interval 0.88 to 1.25.
Homologues: Orthologues: chimpanzee LYPD6B (99% identical), macaque LYPD6B (80% identical), rabbit LYPD6B (79% identical), pig LYPD6B (78% identical), guinea pig LYPD6B (74% identical), dog LYPD6B (73% identical), mouse Lypd6b (72% identical), rat Lypd6b (72% identical), tropical clawed frog lypd6b (46% identical), zebrafish lypd6b (42% identical). Paralogues in human: LYPD6 (29% identical).
Diseases named in the same sentence as LYPD6B in open-access papers:
LYPD6B is named in the same sentence as 20 diseases in open-access papers, as found by Europe PMC text mining. Sharing a sentence is not in itself a finding about the gene and the disease. The quoted sentences say what the papers report.
Anxiety (1 paper, 2024). Intense feelings of nervousness, tension, or panic often arise in response to interpersonal stresses. "We showed that increased abundance of Lypd6 and Lypd6b in the brain was associated with memory decline, anxiety, atrophy of hippocampal and amygdala dendritic spines, and downregulation of the cholinergic system." (PMID 39433742, 2024). "Thus, increased Lypd6 and Lypd6b level in the brain are linked to cholinergic system depression, neuronal atrophy, memory decline, and anxiety." (PMID 39433742, 2024). "Thus, we can assume that impaired memory and anxiety of mice observed here may be driven at least partially by dendritic spine downregulation after ws-Lypd6 and ws-Lypd6b administration." (PMID 39433742, 2024).
autism (1 paper, 2024). Persistent deficits in social interaction and communication and interaction as well as a markedly restricted repertoire of activity and interest as well as repetitive patterns of behavior. "Enhanced mRNA Lypd6 and Lypd6b expression in the brain was found in patients with autism and some other pathologies." (PMID 39433742, 2024). "Bioinformatic analysis revealed increased or decreased LYPD6 and LYPD6B expression in different neuropsychiatric disorders: autism, Parkinson’s and Huntington’s diseases, epilepsy, and others." (PMID 39433742, 2024). "Bioinformatic analysis revealed increased expression of LYPD6 and LYPD6B mRNA expression in the brains of patients with different neurological and psychiatric disorders: autism, Huntington’s and Parkinson’s diseases, and in epilepsy." (PMID 39433742, 2024). "Increased LYPD6 and LYPD6B expression was revealed in autism and other disorders." (PMID 39433742, 2024).
bipolar disorder (1 paper, 2024). A disorder of the brain that causes unusual shifts in mood, energy, activity levels and the ability to carry out day-to-day tasks. "LYPD6B was downregulated in the cortex of patients with bipolar disorder and schizophrenia." (PMID 39433742, 2024). "LYPD6B was upregulated in the cortex of patients with obsessive-compulsive disorder, slightly increased in the cortex and amygdala in major depressive disorder, in the striatum in bipolar disorder and schizophrenia, and in the hippocampus of patients with in chronic alcoholism." (PMID 39433742, 2024).
memory impairment (1 paper, 2024). "Thus, an increase of Lypd6 and Lypd6b levels in the brain leads to stress induction and memory impairment." (PMID 39433742, 2024).
ovarian carcinoma (1 paper, 2022). A malignant neoplasm originating from the surface ovarian epithelium. "It is reported that LYPD6B is expressed in the testes, prostate, stomach, lung, and glutamatergic neurons and that LYPD6B modulates specific nicotinic acetylcholine receptors; upregulated levels of LYPD6B have been associated with ovarian cancer." (PMID 35700824, 2022).
cancer (3 papers, 2020 to 2026). A tumor composed of atypical neoplastic, often pleomorphic cells that invade other tissues. "Immunohistochemistry (IHC) and pan-cancer analyses verified LYPD6B's tumor-cell localization, association with immune infiltration, and checkpoint expression." (PMID 42231559, 2026). "Third, previous studies of LRRC17, ZHX3, LYPD6B, KIAA2022, and CMBL in cancer still remain paucity despite the importance of them." (PMID 31856408, 2020).
hematological malignancies (1 paper, 2020). "Among the identified seven genes (LRRC17, ZHX3, CD38, AKR1B10, LYPD6B, KIAA2022, and CMBL) in our study, CD38 was well known about its correlation with hematological malignancies." (PMID 31856408, 2020).
neurological diseases (1 paper, 2024). "Here, to establish possible relationships between Lypd6 or Lypd6b overexpression in the brain and neurological disorders, we performed bioinformatic analysis of tissues of patients with different neuropsychiatric diseases from the Gene Expression Omnibus." (PMID 39433742, 2024). "To model the upregulation of Lypd6 and Lypd6b in the brain during neurological diseases, we used a mouse model with intracerebroventricular delivery of recombinant water-soluble domains of Lypd6 and Lypd6b (ws-Lypd6 and ws-Lypd6b) into the brain." (PMID 39433742, 2024). "Thus, our data indicate that Lypd6 and Lypd6b may mediate at least some behavioral aspects of certain neurological disorders." (PMID 39433742, 2024). "The correlation between manifestations of neurological disorders and LYPD6 and LYPD6B expression deserves further attention." (PMID 39433742, 2024).
tumor (1 paper, 2026). "Through tumor-intrinsic screening, we identified LYPD6B-a membrane gene upregulated in NR cancer cells that suppresses antigen processing/presentation and IFNα/β signaling." (PMID 42231559, 2026).
LYPD6B also shares sentences with these, for which no sentence is quoted: breast carcinoma (1 paper); cognitive decline (1); epilepsy (1); Huntington disease (1); major depressive disorder (1); malignant melanoma (1); obsessive-compulsive disorder (1); Parkinson disease (1); Parkinson’s (1); psychiatric disorder (1); schizophrenia (1).